ADH1A (alcohol dehydrogenase 1A (class I), alpha polypeptide)
Description:
Alcohol dehydrogenase. Oxidizes primary as well as secondary alcohols. Ethanol is a very poor substrate.
Synonyms: ADH1
Tractability: Small molecule: an approved drug acts on it; a structure with a bound ligand is known; it has a binding pocket of medium quality; it belongs to a druggable protein family. Antibody: its Gene Ontology location is reachable by antibodies, with high confidence. PROTAC: a small molecule that binds it is known.
Target class: Enzyme; Oxidoreductase
Gene: Protein-coding gene on chromosome 4 (99,276,365 to 99,291,552, reverse strand). Ensembl gene ENSG00000187758.
Subcellular location: Cytoplasm
Subcellular location (Human Protein Atlas): Cytosol; Plasma membrane; Basal body; Nucleoplasm; Primary cilium; Primary cilium transition zone
Pathways (Reactome):
Drug ADME: Abacavir metabolism
Metabolism: Ethanol oxidation
Signal Transduction: RA biosynthesis pathway
Gene Ontology:
Molecular function: alcohol dehydrogenase (NAD+) activity; butanol dehydrogenase (NAD+) activity; protein binding; all-trans-retinol dehydrogenase (NAD+) activity; zinc ion binding; oxidoreductase activity
Biological process: alcohol metabolic process; retinoic acid metabolic process; retinol metabolic process
Cellular component: cytosol; cytoplasm
Genetic constraint (gnomAD): Loss-of-function variants: 29 observed, 35.82 expected, observed/expected ratio (o/e) 0.81, 90% interval 0.6 to 1.1. The upper end of that interval is the gene's LOEUF score, 1.1, which puts it in group 4 of 6, group 1 being the genes least tolerant of losing a copy. Missense variants: 460 observed, 470.01 expected, observed/expected ratio (o/e) 0.98, 90% interval 0.91 to 1.06. Synonymous variants: 145 observed, 166.55 expected, observed/expected ratio (o/e) 0.87, 90% interval 0.76 to 1.
Homologues: Orthologues: chimpanzee ADH1A (99% identical), macaque ADH1A (94% identical), mouse Adh1 (83% identical), pig ADH1C (83% identical), rat Adh1c (81% identical), zebrafish zgc:77938 (58% identical), zebrafish adh5l (57% identical), zebrafish adh8a (55% identical), zebrafish adh8b (52% identical), Caenorhabditis elegans D2063.1 (21% identical), Caenorhabditis elegans adh-1 (20% identical), Caenorhabditis elegans sodh-2 (19% identical), and 2 more. Paralogues in human: ADH1B (94% identical), ADH1C (93% identical), ADH7 (69% identical), ADH5 (63% identical), ADH6 (63% identical), ADH4 (60% identical), CRYZ (22% identical), SORD (21% identical), RTN4IP1 (21% identical), VAT1 (21% identical), TP53I3 (20% identical), MECR (19% identical), and 5 more.
Diseases named in the same sentence as ADH1A in open-access papers:
ADH1A is named in the same sentence as 74 diseases in open-access papers, as found by Europe PMC text mining. Sharing a sentence is not in itself a finding about the gene and the disease. The quoted sentences say what the papers report.
hepatocellular carcinoma (6 papers, 2012 to 2022). A malignant tumor that arises from hepatocytes. "ADH1A and aldehyde dehydrogenase 2 (ALDH2) are key regulators of alcohol metabolism, and their suppression aligns well with the gene expression profiles of hepatocellular carcinoma (HCC) and can predict HCC onset and progression." (PMID 36300097, 2022).
liver cancer (6 papers, 2017 to 2025). An epithelial or non-epithelial malignant neoplasm that arises from the liver. "Several reports provide a correlation of ADH1A and other ADHs’ expression with increased risk of liver cancer, with an impact on the prognosis for HCC patients." (PMID 38396873, 2024). "Differential expression of the alcohol dehydrogenase 1A (ADH1A) gene has been observed in biliary stricture and liver cancer." (PMID 36300097, 2022). "ADH4 and ADH1A both belong to the alcohol dehydrogenase (ADH) superfamily and have revealed improved prognostic value in several cancer types, including non-small cell lung cancer, gastric cancer, and liver cancer." (PMID 36341373, 2022).
alcoholism (5 papers, 2010 to 2022). "Previous studies have shown that interactions between SNPs across these genes are apparent in the risk of alcoholism, in particular between ADH1B and ADH7 and between ADH4 and ADH1A." (PMID 23166662, 2012).
breast carcinoma (5 papers, 2020 to 2025). "Nevertheless, our study focused exclusively on the impact of ADH1A expression regulation on breast cancer cells, leaving its variation and mutation status in TNBC inadequately understood." (PMID 41006587, 2025). "Analysis of the TCGA-BRCA cohort data indicates a significant reduction in ADH1A mRNA expression levels across breast cancers with varying degrees of invasiveness, with the most pronounced decrease observed in TNBC." (PMID 41006587, 2025). "Complementary findings from the CPTAC database corroborate this trend, demonstrating a similar reduction in ADH1A protein expression in both high-grade breast cancer and TNBC." (PMID 41006587, 2025). "ADH1A has been found to be a potential biomarker for diagnosis, treatment and prognosis of breast cancer." (PMID 35096840, 2021).
lung carcinoma (4 papers, 2019 to 2021). "Smoking is an important risk factor for lung cancer, a recent study reported that the expression levels of ADHs without ADH1A were significantly associated with smoking status of the NSCLC patients." (PMID 33287761, 2020). "Glutathione S-Transferase Omega 1 (GSTO1), Sulfotransferase Family 2B Member 1 (SULT2B1), ADH1A, ADH1B, and ADH1C were downregulated in lung cancer versus normal tissue, while ALDH3A2 and MTHFD2 were upregulated in lung cancer tissue versus normal adjacent tissue." (PMID 31717324, 2019).
non-small cell lung carcinoma (4 papers, 2019 to 2022). A group of at least three distinct histological types of lung cancer, including non-small cell squamous cell carcinoma, adenocarcinoma, and large cell carcinoma. "As a tumor suppressor, exosome-derived miR-2682-5p can inhibit the viability and migration of non-small-cell lung cancer cells and promote apoptosis through the HDAC1/ADH1A axis." (PMID 35465266, 2022). "High expression of ADH1A or ADH6 was predictive of improved prognosis for pancreatic adenocarcinoma, and high expression of ADH1A or ADH4 had improved prognosis for non-small cell lung cancer." (PMID 31660150, 2019).
Obesity (2 papers, 2015 to 2017). Accumulation of substantial excess body fat. "Winnier’s study provided strong experimental support for the potential roles for ADH1A and ADH1B in obesity, insulin resistance and T2D." (PMID 28496128, 2017). "One possible mechanism of ADH1A and ADH1B in adipose tissue and obesity has been proposed to explain their negative association with obesity-related traits and insulin resistance." (PMID 28496128, 2017).
alcoholic hepatitis (1 paper, 2024). Acute hepatitis resulting from ingestion of alcohol. "However, our analysis of the GSE28691 database showed that ADH1A and ADH1C were downregulated in liver tissues of patients with alcoholic hepatitis, while ADH1B and ADH5 showed no significant changes." (PMID 39044161, 2024).
esophageal cancer (1 paper, 2016). A primary or metastatic malignant neoplasm involving the esophagus. "A proxy SNP (rs1229977, r2 = 0.63) for the G × BMI variant regulating ADH1A (alcohol dehydrogenase 1A), rs1693457, is associated with esophageal cancer (MIM: 133239) in a large GWAS." (PMID 27588447, 2016).
liver failure (1 paper, 2025). A liver disease characterized by the liver losing or has lost all of its function. "Hepatocyte markers ALB, TTR and alcohol dehydrogenase 1A (ADH1A) were not significantly DE between normal and early ALD but were significantly downregulated in AH versus early ALD, suggesting a secondary transcriptomic response following onset of liver failure." (PMID 40122595, 2025).
ovarian carcinoma (1 paper, 2021). A malignant neoplasm originating from the surface ovarian epithelium. "The YAP, TEAD4, and ADH1A proteins appear to be promising biomarkers in the diagnosis of ovarian cancer." (PMID 34205023, 2021). "In our study, we evaluated the expression of class 1 alcohol dehydrogenase (ADH1A) in ovarian cancer tissue and benign and healthy ovary tissue." (PMID 34205023, 2021). "YAP, TEAD4, and ADH1A proteins appear to be promising biomarkers in the diagnosis of ovarian cancer." (PMID 34205023, 2021). "They showed a significant expression of mRNA for ADH1A in ovarian cancer tissue compared to healthy ovarian tissue and benign cysts." (PMID 34205023, 2021). "However, they noted that the activity of the enzyme responsible for ADH1A degradation was the same in ovarian cancer tissue as in healthy tissue." (PMID 34205023, 2021). "Significantly increased expression of ADH1A in ovarian cancer tissue, with disproportionately unincreased levels of aldehyde dehydrogenase (degradation enzyme), may lead to the increased production of acetaldehyde and the support of carcinogenesis in ovarian tissue." (PMID 34205023, 2021).
triple-negative breast carcinoma (1 paper, 2025). An invasive breast carcinoma which is negative for expression of estrogen receptor (ER), progesterone receptor (PR), and human epidermal growth factor receptor 2 (HER2). "A Venn diagram further identified three potential key TRGs in triple-negative breast cancer (TNBC), namely ADH1A, AOC2, and TYRP1." (PMID 41006587, 2025).
tumor (45 papers, 2012 to 2025). "In addition, we explored the relationship between the TRGs risk model and TME, and revealed the strong association of METTL6, LCMT1, GSTZ1, ADH4, and ADH1A with the tumor immune infiltration and immune checkpoints." (PMID 36341373, 2022). "Consistently, a reduction in the expression of ADH1A has been observed in hepatocarcinoma tissue compared with para-tumor tissues, and this pattern is also evident in C3 compared with C1 and C2." (PMID 40666097, 2025). "While this study elucidates ADH1A’s tumor-suppressive mechanism at the cellular level, we acknowledge that validation in in vivo models is warranted to fully characterize its therapeutic potential." (PMID 41006587, 2025). "ADH4, GSTZ1, and ADH1A were downregulated in HCC tumor tissues compared with the normal tissues, which were consistent with their role in HCC." (PMID 36341373, 2022). "We observed that ADH4, GSTZ1, and ADH1A were downregulated in HCC tumor tissues, while the LCMT1 was overexpressed in HCC tumor tissues compared with the normal tissues, which were consistent with the mRNA expression level of HCC." (PMID 36341373, 2022). "Our results showed that the expression level of ADHs including ADH1A, ADH1B, ADH1C, and ADH6 was obviously decreased with the progression of tumor malignancy." (PMID 33287761, 2020). "Alcohol dehydrogenase 1A (ADH1A), CAT, GAPDH, and MDH2 were related to the generation of precursor metabolites and energy, which played an important role in the proliferation of tumor cells." (PMID 37124724, 2023). "The expression levels of FCGBP, PABPC1 and NDRG1 were higher and the expression levels of ADH1A, CYP3A4 and ADH1B were lower in tumour tissues than in adjacent nontumour tissues." (PMID 35109839, 2022).
cancer (26 papers, 2012 to 2025). A tumor composed of atypical neoplastic, often pleomorphic cells that invade other tissues. "ADH polymorphisms correlate with cancer risk, and they encompass three gene loci (ADH1A, ADH1B, ADH1C) containing genetic variations that elevate cancer risk, particularly with heavy alcohol consumption." (PMID 41148854, 2025). "On the other hand, the hypermethylation of ADHFE1 further reduced the expression of neighbouring proteins, ADH6, ADH7, as well as ADH1A, in which the genes were associated with the patient’s prognosis and cancer pathogenesis." (PMID 35054365, 2022). "Further population-based research is required to elucidate the function of ADH1A in various cancers." (PMID 41006587, 2025). "Other genes such as CYP3A4, CYP2C9, ADH4, ADH1A, and CYP1A2 enriched in the cytochrome P450 pathway are observed as metabolically active procarcinogens to genotoxic intermediates, and an association has been found between CYP enzyme activity and the risk to develop several forms of cancer." (PMID 31024618, 2019). "Our results are consistent with a previous study that observed class I ADH (including ADH1A, ADH1B and ADH1C) to be more highly expressed, at both mRNA and protein levels, in normal breast tissues from cancer-free women than in invasive breast tumor tissues." (PMID 28899409, 2017).
ADH1A also shares sentences with these, for which no sentence is quoted: Hypercalciuria (11 papers); Hypocalcemia (11); infection (11); hypoparathyroidism (10); melanoma (7); pancreatic cancer (6); Autosomal Dominant Hypocalcemia Type 1 (5); neuroblastoma (4); gastric cancer (3); hyperphosphatemia (3); leukemia (3); alcoholic liver diseases (2); Bartter syndrome type V (2); colorectal cancer (2); liver fibrosis (2); metastatic melanoma (2); multiple myeloma (2); nephrocalcinosis (2); nephrolithiasis (2); vitamin A deficiency (2); Zinc deficiency (2); adenoma (1); airway hyperresponsiveness (1); amyloidosis (1); angiomyolipoma (1); asthma (1); autosomal dominant disease (1); autosomal dominant hypocalcemia (1); autosomal dominant hypoparathyroidism (1); Bartter syndrome (1).
A further 30 diseases each share a sentence with ADH1A in 1 paper.